HLA-DRB1 (major histocompatibility complex, class II, DR beta 1)
Diseases named in the same sentence as HLA-DRB1 in open-access papers (continued):
Sharing a sentence is not in itself a finding about the gene and the disease.
Alzheimer disease (14 papers, 2012 to 2024). A progressive, neurodegenerative disease characterized by loss of function and death of nerve cells in several areas of the brain leading to loss of cognitive function such as memory and language. "We report that specific HLA-DRB1*04 alleles are protective against Alzheimer’s dementia (AD), Parkinson’s disease (PD), and other neurodegenerative disorders." (PMID 37643212, 2023). "Genome-wide association studies (GWAS) have identified one single-nucleotide polymorphism (SNP) rs9271192 within HLA-DRB1 as a risk factor for Alzheimer's disease (AD) in Caucasians." (PMID 29190991, 2017). "In the Alzheimer’s Disease Neuroimaging Initiative cohort study, it was found that the HLA-DRB1/DQB1 allele variant may regulate the volume of the left posterior cingulate gyrus and affect the susceptibility of AD." (PMID 34447367, 2021). "In contrast, peptides deriving from microtubule-associated protein tau, presenilin 2 and serine/threonine-protein kinase TBK1 were exclusively reported to bind MHC molecules encoded by the HLA-DRB1 1501 allele, a recently-identified susceptibility gene for late onset Alzheimer's disease." (PMID 31824497, 2019). "At P<2.5×10−6, we found significant associations with risk of Alzheimer’s disease for APOC1 (Z = 4.84, P = 1.29×10−6) and HLA-DRB1 (Z = 6.80, P = 1.05×10−11) that also passed permutation testing." (PMID 33684137, 2021). "For example, the association between HLA-A*01, A*2402, HLA-DRB1*03 or DRB1*1501 and high risk for Alzheimer disease has been reported." (PMID 23139797, 2012). "Genetic studies including genome-wide studies have also associated inflammation-related genes to the etiology of Alzheimer’s disease (i.e. ABCA7, CLU, CR1, HLA-DRB1, HLA-DRB5, PICALM, and TREM2), further supporting the concept of neuroinflammation as a pathogenic factor in Alzheimer’s disease." (PMID 34335238, 2021).
influenza (14 papers, 2013 to 2025). An acute viral infection of the respiratory tract, occurring in isolated cases, in epidemics, or in pandemics; it is caused by serologically different strains of viruses (influenzaviruses) designated A, B, and C, has a 3-day incubation period, and usually lasts for 3 to 10 days. "The allele HLA-DRB1*04:01 has been observed to confer greater resistance to influenza (H1N1) by eliciting robust immune responses through more effective T cell activation and increased interferon-gamma (IFN-γ) production." (PMID 41425584, 2025). "The presence of HLA-DRB1*07*15 in the genotype of pregnant women is associated with a severe course of influenza." (PMID 41305516, 2025). "Specifically, two strains expressing HLA-DRB1*04:01 and HLA-DRB1*04:02, respectively, were compared, and although both developed immunity to influenza infection, only the *0401 mice generated a more intense cross-protective immunity." (PMID 41425584, 2025). "Using pMHCII-tetramer technology, we analyzed HA118-132- and HA306-318-specific CD4 T cells ex vivo in HLA-DRB1*01:01-positive individuals who received influenza vaccination in 2016/2017, 2018/2019, 2019/2020, and/or 2020/2021." (PMID 34795301, 2021). "For example, HLA-DRB1*13:02 has been shown to confer protection against various illnesses ranging from hepatitis B and C, influenza, HIV, malaria, and numerous autoimmune disorders." (PMID 31031617, 2019). "The aim of the present study was to evaluate the immunogenicity of double restricted influenza-derived 9-11mer peptides in HLA-A*02:01/HLA-DRB1*01:01 transgenic mice." (PMID 26731261, 2016). "PBMCs were collected from six HLA-DRB1*04:01-positive subjects before vaccination and after receiving the 2014–2015 seasonal northern hemisphere influenza vaccine." (PMID 27571776, 2016). "Thus, variants associated with a severe course of influenza were found: HLA-A*11, HLA-B*35, HLA-DRB1*10, and HLA-DRB1*01*01." (PMID 41305516, 2025). "In this context, HLA-DRB1*04:01 and HLA-DRB1*03:01, by conferring greater cross-immunity with different influenza strains, could have provided an additional immunological advantage against the Spanish influenza virus, favoring their selection in subsequent generations." (PMID 41425584, 2025). "The protective role of the HLA genotypes HLA-DRB1*01*04, HLA-DRB1*07*08, and HLA-DRB1*11*13 against influenza AH1N1pdm2009 has been described in the literature." (PMID 41305516, 2025). "The combined presence of genotypes HLA-F7:0976GA, HLA-PAI-1:6754G4G and HLA-DRB1*07*15, HLA-DRB1*16*16, HLA-DRB1*01*01 may be a predictor of the development of severe forms of influenza." (PMID 41305516, 2025). "On PSLB, CD40L localizes to the center of the IS predominantly in the presence of CD40 and HLA-DRB1*09:01-influenza HA338-355, not in the presence of HLA-DRB1*09:01:CLIP." (PMID 31469364, 2019). "Moreover, a positive association between non-responsiveness to influenza vaccine and HLA-DRB1*07 and a negative association with HLA-DRB1*13 and HLA-DQB1*0603-9/14 was reported, suggesting that polymorphisms in HLA class II molecules affect antibody responses to IAV vaccination." (PMID 31574965, 2019).
schizophrenia (14 papers, 2012 to 2025). A major psychotic disorder characterized by abnormalities in the perception or expression of reality. "Currently, there are convincing evidence that allelic variants of HLA genes, including HLA-DQB1*0602 and HLA-DRB1*04, can affect the risk of schizophrenia." (PMID 40416497, 2025). "NMNAT2 is important for the maintenance of neurons and is known to be neuroprotective in several models of neurological disorders, while HLA-DRB1 is the most frequently reported genetic association to schizophrenia." (PMID 33892787, 2021). "Very few studies, to date, have examined the correlation between the structure of the HLA-DRB1 polymorphism and GD, schizophrenia, and T2D." (PMID 28174595, 2017). "The GWAS studies to date have not found the gene(s) responsible or causative variants in the MHC locus, although the HLA-B and HLA-DRB1 loci were protective, and the HLA-C increased risk for schizophrenia." (PMID 26998349, 2016). "The trend of association found between the DR4 allele of HLA-DRB1 in our probands with language-impairment matches that described by Wright and colleagues in a study of schizophrenia but is the opposite of that observed in ADHD by Odell and colleagues." (PMID 24433325, 2014). "We also found that SNPs influencing the expression of HLA-DRB1 (expression quantitative trait loci - eQTLs) were significantly associated with schizophrenia in the CATIE and MGS datasets (unpublished data)." (PMID 23282246, 2012). "Furthermore, the HLA-DRB1 gene has been a focus in investigating the HLA association with schizophrenia." (PMID 28174595, 2017). "HLA-DRB1 has been reported for positive association with schizophrenia." (PMID 23282246, 2012). "In another study the HLA-DRB1*03 allele, a component of the HLA-DRB1*01/*03 genotype, was identified as exerting a protective role against schizophrenia." (PMID 41155473, 2025). "Numerous studies have demonstrated association between HLA alleles (HLA-A9, HLA-A10, HLA-DRB1, HLA-DQB1) and schizophrenia susceptibility." (PMID 31642026, 2020). "A strong positive association between HLA-DRB1*03 and HLA DQB1*02 alleles and schizophrenia has widely been reported in the Saudi and Tunisian populations." (PMID 28174595, 2017). "Within this interval we examined the expression of two MHC II genes (HLA-DPA1 and HLA-DRB1) in brain from individual subjects with schizophrenia (SZ), bipolar disorder (BD), major depressive disorder (MDD), and controls by differential gene expression methods." (PMID 26998349, 2016). "Five genes (SELL, HLA-DRB1, CEBPD, HSPA5, and NRGN) from the matched list had been previously studied for schizophrenia with positive association signals, the rest of the genes were involved in immune responses or other neuronal diseases." (PMID 23282246, 2012). "The interaction among HLA-C, HLA-DRB1, and HLA-DQB1 is likely to take part in schizophrenia’s pathogenesis as well." (PMID 34805976, 2021). "No studies have been conducted on specific mechanisms of HLA-C, HLA-DRB1, and HLA-DQB1’s interventions in schizophrenia pathogenesis, but their interaction is much likely to contribute to the disease." (PMID 34805976, 2021). "Moreover, focusing on adaptive immunity, the most studied loci in primary psychosis, especially in schizophrenia, are HLA- A, B, and C of the antigen-presenting Major Histocompatibility Complex (MHC), Class I and HLA-DRB1 and DQB1 of the MHC, Class II." (PMID 34829493, 2021). "Specific alleles (please see a note regarding the terminology in the Methods section) of HLA-DRB1, including DR4 and DR12, have been associated with autism, ADHD, and schizophrenia, although these findings have not always replicated within or between disorders." (PMID 24433325, 2014).
vitiligo (14 papers, 2009 to 2025). Generalized well circumscribed patches of leukoderma that are generally distributed over symmetric body locations and is due to autoimmune destruction of melanocytes. "Similar to previous studies, our findings suggest that mutations in the MHC region of vitiligo exist in multiple HLA genes, including but not limited to HLA‐A, HLA‐DRB1, HLA‐B, HLA‐C, and so on." (PMID 40657813, 2025). "Variants in HLA genes, particularly HLA-DQB1 and HLA-DRB1, are strongly linked to increased susceptibility to vitiligo." (PMID 39860439, 2025). "Our study reaffirms previous reports linking HLA‐A, HLA‐C, and HLA‐DRB1 to vitiligo, and further validates the association of HLA‐C with freckles." (PMID 40657813, 2025). "HLA-DRB1*07 has been reported to be associated with vitiligo, especially early-onset vitiligo in Asian populations and African populations." (PMID 35082778, 2021). "Recently, we have shown positive association of HLA-A*33:01, HLA-B*44:03, and HLA-DRB1*07:01 with vitiligo patients from North India and Gujarat suggesting an autoimmune link of vitiligo in these cohorts." (PMID 23284977, 2012). "HLA-DRB1*03, HLA-DRB1*04 and HLA-DRB1*07 alleles were found to be associated with vitiligo in Turkish patients, and the association of HLA-DRB4*0101 and HLA-DRB4*0303 alleles was found in Dutch patients." (PMID 19543371, 2009). "HLA-DRB1*07 was associated with vitiligo in Brazil, the Netherlands and India." (PMID 31505868, 2019). "To dissect the relative contributions of rs149554018, rs9271597, and the classical HLA alleles to vitiligo risk, we compared logistic regression models with haplotypes defined by different combinations of rs145954018, HLA-DRB1*13:01, rs9271597, HLA-DQA1*01:03, and HLA-DQB1*06:03." (PMID 30674883, 2019). "Furthermore, we also found suggestive epistatic effect between rs2269577 and HLA-DRB1*07 allele on the development of vitiligo (p = 0.033)." (PMID 19543371, 2009). "HLA alleles implicated in vitiligo and found so far are HLA-DRB4*0101, HLA-DQB1*0303, HLA-DRB1*03, HLA-DRB1*04, HLA-DRB1*07, and HLA DRB1A*04-(DQA1*0302)-DQB1*0301." (PMID 36902341, 2023). "In the Turkish population, the HLA-DRB1*01 allele is protective against vitiligo in terms of oxidative stress; for patients who do not carry the HLA-DRB1*01 allele, the TAC (total antioxidant capacity) level in serum is significantly lower." (PMID 35082778, 2021). "Using Beagle 4.1, we successfully imputed the SNV, CNV, two–digit and four–digit alleles of HLA genes (HLA-A, HLA-B, HLA-C, HLA-DQA1, HLA-DQB1, HLA-DPA1, HLA-DPB1, HLA-DRB1) and amino acids of 2810 vitiligo subjects (1117 cases, 1693 controls) and 2739 SLE subjects (1,693 controls and 1,046 cases)." (PMID 35082778, 2021). "Several studies have probed the role HLA-DRB1 plays in vitiligo." (PMID 35082778, 2021). "Similarly to HLA-A, an enhancer located between HLA-DRB1 and HLA-DQA1 genes regulates their expression, leading to the conclusion that the expression level of HLA class II molecules is as or more important than antigen specificity for vitiligo risk." (PMID 31505868, 2019).
Allergy (12 papers, 2011 to 2024). An allergy is an immune response or reaction to substances that are usually not harmful. "For instance, HLA-DRB1*11 is associated with an increased risk of developing allergies to certain pollens, while HLA-DQ2 and HLA-DQ8 are linked to celiac disease, a condition triggered by an immune response to gluten." (PMID 39204201, 2024). "We found both shrimp and peach allergy to be associated with variants that are eQTLs for HLA-DQA2 gene expression as well as associated with specific HLA-DRB1 and HLA-DQB1 alleles." (PMID 29348432, 2018). "Specifically, the HLADRB1*07:01 allele is well recognized as being associated with a high risk of hypersensitivity reactions and a higher risk of allergies after treatment with bacterial ASNase, possibly because it is an allele that confers high-affinity binding." (PMID 38732010, 2024). "These shrimp allergy-associated genes include HLA-DQ (rs9275596), HLA-DRB1 (HLA-DRB1*04:05-HLA-DQB1*04:01), IL-13 (rs20541, and IL13 rs1800925), and food allergy -associated gene TLR4 rs4986790 (Asp299Gly)." (PMID 39493746, 2024). "ATF5 and EFS, ASNS and allergy/pancreatitis, GRIA1 and hypersensitivity, HLA-DRB1*0701 and allergy, CPA2 and pancreatitis)." (PMID 28574850, 2017). "With this understanding, it is feasible that these high binders to HLA-DRB1*03:01 could serve as T-cell epitopes and hold promise as potential candidates for allergy immunotherapy." (PMID 39204201, 2024).
autoimmune thyroid disease (12 papers, 2012 to 2025). Inflammatory disease of the thyroid gland due to autoimmune responses leading to lymphocytic infiltration of the gland. "Non-synonymous variants in HLA-DRB1 have been associated with autoimmune thyroiditis in humans and in mice." (PMID 22493691, 2012). "The results of the cross tabulation between the dependent variable (autoimmune thyroid disease) and the independent variables (the occurrence of each of the HLA-DRB1 allele groups) for the entire sample (77 cases and 135 controls) brought out some significant results." (PMID 38672712, 2024). "The aim of our study was to establish correlations of HLA-DRB1 and -DQB1 allele groups with autoimmune thyroid diseases (HT and BGD) in the population of northwestern Romania." (PMID 38672712, 2024). "However, it is well known that HLA-DRB1*03 is associated with an increased risk of all thyroid autoimmune diseases, not exclusively with GD." (PMID 35566618, 2022). "Notably, genes like HLA-DRB1 and HLA-DRB5, situated in or near the human major histocompatibility complex (MHC) on chromosome 6, exhibit associations with immune diseases (e.g., autoimmune thyroid disease) and cardiovascular traits (e.g., coronary artery disease)." (PMID 38384714, 2024).
lymphoma (12 papers, 2011 to 2025). A malignant (clonal) proliferation of B- lymphocytes or T- lymphocytes which involves the lymph nodes, bone marrow and/or extranodal sites. "This also applies to HLA-DRB1*11 and HLA-DRB1*12 and Epstein-Barr virus-associated lymphoma." (PMID 39859309, 2025). "Among these binding sites, cell culture experiments using lymphoma B cells identified an X box-like element named XL9 between the two diametrically transcribed genes HLA-DRB1 and HLA-DQA1." (PMID 30212590, 2018). "For example, upregulated proteins such as HLA-DRB1, CD22, CD74, and CD8A are consistent with established roles in lymphoid malignancies and oncogenic signaling, supporting prior studies identifying CD74 as a diagnostic and therapeutic target in lymphomas." (PMID 41035678, 2025). "Interestingly, for the single lymphoma patient with available HLA data and T cell specificity, our predictions confirmed high affinity of the eluted VH peptide to HLA-DRB1*04:01 molecules [predicted ln(IC50) = 3.69, SD = 0.69]." (PMID 29038659, 2017). "B cells were isolated and immortalized from PBMC samples of three lymphoma patients, respectively Pt.2 (HLA-DRB1*0701), Pt.5 (HLA-A*0201 and HLA-DRB1*0701), and Pt.7 (HLA-A*0201 and HLA-DRB1*0701)." (PMID 36979775, 2023).
malaria (12 papers, 2009 to 2023). Malaria is a serious and sometimes fatal disease caused by a parasite that commonly infects a certain type of mosquito which feeds on humans. "Nevertheless, establishing the relationship between these HLA-DRB1 alleles and malaria warrants further validation through additional functional experiments." (PMID 26230582, 2015). "Some of these (e.g., for HLA-DRB1*01:01 or HLA-DRB1*04:01) supported the hypothesis that malaria risk varies in parallel with MHC allele frequency across countries." (PMID 25187124, 2014). "In malaria patients, HLA-DRB1*07 alleles were correlated with improved antibody responses against both domains of the chimeric protein PfCP-2.9 (P. falciparum apical membrane antigen-1, PfAMA-1, and PfMSP-119) but HLA-DRB1*08 had the contrary effect on PfAMA-1 and PfMSP-119." (PMID 22649493, 2012). "For example, HLA allele polymorphisms HLA- B*5301, HLA- DRB1*1302, and HLA- DRB1*0101 have been associated with genetic resistance or HLA-DRB1*04 with susceptibility to malaria, but the distribution is different in different populations where malaria is endemic." (PMID 21087485, 2010). "In addition other unidentified risk variants are also likely to be present and studies in a larger population from different malaria endemic regions of Southeast Asia and Africa are necessary to give support to the HLA-DRB1*04 allele association with antibody responses." (PMID 22649493, 2012). "Thus, HLA-DRB*101:01 (PDB code 1aqd) and HLA-DRB1*04:01 (1q94) were alleles for malaria resistance and susceptibility, respectively." (PMID 36985500, 2023). "We carried out systematic identification and verification of predicted class II T cell epitopes for five Pf blood stage antigen vaccine targets to better enable blood stage malaria vaccine design through identification and validation of highly promiscuous HLA-DRB1-restricted epitope clusters." (PMID 34305923, 2021). "HLA-DRB1*01 was also negatively associated with repetitive regions of P. vivax MSP-9 antigen in the Brazilian Amazon, and HLA-DQB1*05 along with HLA-DRB1*13 has been associated with a reduced susceptibility to severe malaria in Gambian children." (PMID 29754588, 2018). "Together, these data raise the hypothesis that pathogen-driven selective forces, particularly malaria (believed to have exerted a selective pressure on the immune system), induced the high frequency of the HLA-DQB1*02 and HLA-DRB1*13 alleles in the Ethiopian population." (PMID 22761960, 2012). "Frequency (F) and number (n) of IgG responders and non-responders to the PvRMC-RBP1and Pv-RBP123-751 recombinant proteins tested by HLA-DRB1* and HLA-DQB1*allelic groups from individuals naturally exposed to malaria." (PMID 25148251, 2014). "Frequency (F) and number (n) of IgG responders and non-responders to the PvMSP-9 and PvMSP-1 recombinant proteins tested by HLA-DRB1* and HLA-DQB1*allelic groups from malaria naturally exposed individuals." (PMID 22649493, 2012). "The effects of different HLA-DRB1 and HLA-DQB1 allelic groups and time of residence (years) in malaria endemic areas on the level of antibodies to PvMSP-1, PvMSP-3α and PvMSP-9, were also analyzed." (PMID 22649493, 2012).